STAT3 (signal transducer and activator of transcription 3)
Description:
Signal transducer and transcription activator that mediates cellular responses to interleukins, KITLG/SCF, LEP and other growth factors. Once activated, recruits coactivators, such as NCOA1 or MED1, to the promoter region of the target gene. May mediate cellular responses to activated FGFR1, FGFR2, FGFR3 and FGFR4. Upon activation of IL6ST/gp130 signaling by interleukin-6 (IL6), binds to the IL6-responsive elements identified in the promoters of various acute-phase protein genes. Activated by IL31 through IL31RA. Acts as a regulator of inflammatory response by regulating differentiation of naive CD4(+) T-cells into T-helper Th17 or regulatory T-cells (Treg): acetylation promotes its transcription activity and cell differentiation while deacetylation and oxidation of lysine residues by LOXL3 inhibits differentiation. Involved in cell cycle regulation by inducing the expression of key genes for the progression from G1 to S phase, such as CCND1. Mediates the effects of LEP on melanocortin production, body energy homeostasis and lactation (By similarity). May play an apoptotic role by transctivating BIRC5 expression under LEP activation. Cytoplasmic STAT3 represses macroautophagy by inhibiting EIF2AK2/PKR activity. Plays a crucial role in basal beta cell functions, such as regulation of insulin secretion (By similarity). Following JAK/STAT signaling activation and as part of a complex with NFATC3 and NFATC4, binds to the alpha-beta E4 promoter region of CRYAB and activates transcription in cardiomyocytes (By similarity). Involved in the oncostatin-M-mediated signaling pathway through both type I OSM receptor complex (heterodimers composed of LIFR and IL6ST) and type II OSM receptor complex (heterodimers composed of OSMR and IL6ST).
Synonyms: APRF; ADMIO; ADMIO1; HIES
Tractability: Small molecule: a structure with a bound ligand is known; a high-quality ligand is known; it belongs to a druggable protein family. Antibody: its Gene Ontology location is reachable by antibodies, with medium confidence. PROTAC: it is named in the literature on targeted protein degradation; ubiquitination databases record sites on it; its protein half-life has been measured; a small molecule that binds it is known.
Target class: Transcription factor
Chemical probes: ML115, ML116, SD-36 (high quality)
Gene: Protein-coding gene on chromosome 17 (42,313,324 to 42,388,568, reverse strand). Ensembl gene ENSG00000168610.
Subcellular location: Cytoplasm; Nucleus
Subcellular location (Human Protein Atlas): Cytosol; Nucleoplasm
Pathways (Reactome):
Immune System: Growth hormone receptor signaling; Inactivation of CSF3 (G-CSF) signaling; Interleukin-10 signaling; Interleukin-15 signaling; Interleukin-20 family signaling; Interleukin-21 signaling; Interleukin-23 signaling; Interleukin-27 signaling; Interleukin-35 Signalling; Interleukin-37 signaling; Interleukin-4 and Interleukin-13 signaling; Interleukin-6 signaling; Interleukin-7 signaling; Interleukin-9 signaling; PKR-mediated signaling; Regulation of PD-L1(CD274) transcription; Signaling by CSF1 (M-CSF) in myeloid cells; Signaling by CSF3 (G-CSF)
Signal Transduction: Downstream signal transduction; MET activates STAT3; PTK6 Activates STAT3; STAT3 nuclear events downstream of ALK signaling; Signaling by ALK; Signaling by Leptin; Signaling by SCF-KIT; Signalling to STAT3
Disease: Nuclear events stimulated by ALK signaling in cancer; Signaling by ALK fusions and activated point mutants; Signaling by PDGFRA extracellular domain mutants; Signaling by PDGFRA transmembrane, juxtamembrane and kinase domain mutants; Signaling by cytosolic FGFR1 fusion mutants; Signaling by phosphorylated juxtamembrane, extracellular and kinase domain KIT mutants
Developmental Biology: POU5F1 (OCT4), SOX2, NANOG activate genes related to proliferation; Transcriptional regulation of granulopoiesis; Transcriptional regulation of pluripotent stem cells
Cellular responses to stimuli: Cytoprotection by HMOX1; Senescence-Associated Secretory Phenotype (SASP)
Cell-Cell communication: Activation of STAT3 by cadherin engagement
Metabolism of proteins: Association of TriC/CCT with target proteins during biosynthesis
Programmed Cell Death: BH3-only proteins associate with and inactivate anti-apoptotic BCL-2 members
Gene Ontology:
Molecular function: chromatin DNA binding; DNA-binding transcription activator activity, RNA polymerase II-specific; DNA-binding transcription factor activity; DNA-binding transcription factor activity, RNA polymerase II-specific; DNA-binding transcription factor binding; identical protein binding; lncRNA binding; nuclear receptor activity; primary miRNA binding; protein binding; protein homodimerization activity; protein phosphatase binding; RNA binding; RNA polymerase II cis-regulatory region sequence-specific DNA binding; RNA polymerase II-specific DNA-binding transcription factor binding; RNA sequestering activity; signaling adaptor activity; signaling receptor binding; transcription cis-regulatory region binding; DNA binding; protein dimerization activity; protein kinase binding; protein sequestering activity; CCR5 chemokine receptor binding; nuclear glucocorticoid receptor binding; and 1 more
Biological process: cell differentiation; cell surface receptor signaling pathway via JAK-STAT; cell surface receptor signaling pathway via STAT; cellular response to hormone stimulus; cellular response to leptin stimulus; ciliary neurotrophic factor-mediated signaling pathway; cytokine-mediated signaling pathway; growth hormone receptor signaling pathway; growth hormone receptor signaling pathway via JAK-STAT; interleukin-10-mediated signaling pathway; interleukin-11-mediated signaling pathway; interleukin-15-mediated signaling pathway; interleukin-19-mediated signaling pathway; interleukin-2-mediated signaling pathway; interleukin-23-mediated signaling pathway; interleukin-6-mediated signaling pathway; interleukin-9-mediated signaling pathway; intracellular receptor signaling pathway; leptin-mediated signaling pathway; leukemia inhibitory factor signaling pathway; negative regulation of autophagy; negative regulation of gene expression; negative regulation of inflammatory response to wounding; negative regulation of primary miRNA processing; oncostatin-M-mediated signaling pathway; and 63 more
Cellular component: chromatin; cytoplasm; cytosol; nucleoplasm; nucleus; RNA polymerase II transcription regulator complex; transcription regulator complex; plasma membrane; glutamatergic synapse; mitochondrial inner membrane; postsynaptic density; Schaffer collateral - CA1 synapse
Genetic constraint (gnomAD): Loss-of-function variants: 7 observed, 120.13 expected, observed/expected ratio (o/e) 0.0583, 90% interval 0.032 to 0.11. The upper end of that interval is the gene's LOEUF score, 0.11, which puts it in group 1 of 6, group 1 being the genes least tolerant of losing a copy. Missense variants: 364 observed, 1,005 expected, observed/expected ratio (o/e) 0.36, 90% interval 0.33 to 0.4. Synonymous variants: 331 observed, 374.61 expected, observed/expected ratio (o/e) 0.88, 90% interval 0.81 to 0.97.
Gene-disease validity (ClinGen):
ClinGen rates the evidence that STAT3 causes each of these diseases.
hyper-IgE recurrent infection syndrome 1, autosomal dominant (autosomal dominant): Definitive.
Cancer hallmarks: change of cellular energetics (promotes); escaping immune response to cancer (promotes); angiogenesis (promotes); tumour promoting inflammation; cell replicative immortality; escaping programmed cell death (promotes); proliferative signalling (promotes); tumour promoting inflammation (promotes); invasion and metastasis (promotes); genome instability and mutations (suppresses); genome instability and mutations; genome instability and mutations (promotes)
Homologues: Orthologues: macaque STAT3 (100% identical), mouse Stat3 (99% identical), rabbit STAT3 (99% identical), rat Stat3 (99% identical), dog STAT3 (99% identical), guinea pig STAT3 (99% identical), pig STAT3 (96% identical), tropical clawed frog stat3 (96% identical), chimpanzee STAT3 (96% identical), zebrafish stat3 (88% identical), Caenorhabditis elegans sta-1 (22% identical), Caenorhabditis elegans sta-2 (15% identical). Paralogues in human: STAT1 (51% identical), STAT4 (47% identical), STAT2 (38% identical), STAT5B (29% identical), STAT5A (28% identical), STAT6 (24% identical).
Diseases named in the same sentence as STAT3 in open-access papers:
STAT3 is named in the same sentence as 1,165 diseases in open-access papers, as found by Europe PMC text mining. Sharing a sentence is not in itself a finding about the gene and the disease. The quoted sentences say what the papers report.
breast cancer (2,208 papers, 1995 to 2026). A primary or metastatic malignant neoplasm involving the breast. "In a retrospective cohort of early-stage HER2+ breast cancer, high stromal S100-A11 expression was associated with residual disease after neoadjuvant therapy and with increased tumour p-STAT3 levels." (PMID 42155177, 2026). "While constitutive STAT3 activation is common in advanced breast cancer, the underlying mechanisms vary with the complex microenvironment." (PMID 41480760, 2026). "Overactivation of STAT3 signaling has been associated with breast cancer progression, metastasis, and therapeutic resistance." (PMID 41480760, 2026). "Sustained activation of STAT3 is closely associated with various types of tumors, including OC, breast cancer, prostate cancer, and lung cancer." (PMID 41158754, 2026). "LIFR/STAT3 axis, expressed in breast cancer cells, has been implicated in maintaining dormancy within the bone niche." (PMID 41596432, 2026). "CDDO-Im downregulates the growth and metastasis of breast cancer by blocking the Epidermal growth factor receptor (EGFR)/Signal Transducer and Activator of Transcription 3 (STAT3)/Sox-2 pathways in Tumor-associated macrophages (TAMs)." (PMID 39926108, 2025). "To provide functional evidence that STAT3 inhibition is sufficient to render cells deficient in FA pathway activity, we tested the melphalan sensitivity of breast cancer cells invalidated for STAT3 expression versus cells invalidated for FANCD2 expression." (PMID 40038300, 2025). "Given the recent reports suggesting an interaction between NRF2 and STAT3 in breast cancer cells, we aimed to determine if a similar association exists in SCC cells." (PMID 40317079, 2025). "Activation of the IL-6/JAK/STAT3 pathway has been reported in many tumor types including breast, and additionally elevated serum levels of IL-6 in breast cancer patients have been linked to poor prognosis." (PMID 40597443, 2025). "Under pathogenic conditions, STAT3 overexpression drives breast cancer cell progression and proliferation while inhibiting apoptosis and orchestrating immune suppression." (PMID 41597595, 2025). "Signal transducer and activator of transcription 3 (STAT3) and STAT5 are both highly involved in breast cancer; however, STAT3 activity is often associated with more aggressive subtypes." (PMID 40507264, 2025). "Circulating FABP4 promoted obesity-associated breast cancer by increasing mammary tumor stemness and aggressiveness through the IL-6/STAT3/ALDH1 axis." (PMID 41392988, 2025). "For example, CSCs in breast cancer express the CD44s variant, which activates PDGFRβ/STAT3 signaling." (PMID 40647402, 2025). "Overexpression of RAN has been associated with increased cellular proliferation in breast cancer, while persistent STAT3 activation has long been implicated in psoriasis." (PMID 40959079, 2025). "Specifically, elevated CSE expression levels have been firmly established to be closely associated with breast cancer progression related to the STAT3 signaling pathway." (PMID 41323827, 2025). "Persistent STAT3 activation has been observed in breast cancer, suggesting a direct association with oncogenic signaling." (PMID 40166646, 2025). "High sclerostin expression has been shown to be associated with breast cancer bone metastasis; perhaps most interestingly in light of findings presented within this study, sclerostin has been shown to interact with STAT3 to enhance TGF-β/K-Ras signalling." (PMID 40192943, 2025). "STAT3 has been implicated in breast cancer tumorigenesis and has been proposed as a potential therapeutic target, where STAT3 is inappropriately activated in approximately 70% of breast cancers." (PMID 40507264, 2025). "This is consistent with our previous study in a cohort of 527 breast cancer patients which showed that high expression of cytoplasmic STAT3 was associated with reduced outcome while low expression of nuclear STAT3 was associated with poor outcomes." (PMID 40597443, 2025).
breast cancer (continued). "The results demonstrated a moderate and strong positive correlation between these signatures, in basal (r = 0.5255) and luminal A (r = 0.7925) subtypes, respectively, suggesting a positive association between redox activity of APE1 and STAT3 in breast cancer." (PMID 41090323, 2025). "For instance, lncRNA HAGLROS sponges miR‐135b‐3p to block its degradation of COL10A1, resulting in COL10A1‐mediated STAT3 phosphorylation and activation of the IL‐10/STAT3 signaling loop that drives breast cancer‐associated M2 polarization." (PMID 41360672, 2025). "In breast cancer cases, STAT3 has been implicated in the development of resistance to cyclin-dependent kinase 4/6 inhibitors such as Palbociclib." (PMID 38339245, 2024). "Meanwhile, PPI analysis showed that APOE and STAT3 seem to play a pivotal role in all proteins and are strongly associated with the development of breast cancer." (PMID 38887235, 2024). "For example, miR-106a5p/STAT3 axis is associated with the development and ferroptosis in breast cancer." (PMID 38358587, 2024). "The sustained stimulation of signal transducer and activator of transcription 3 (STAT3) has been linked to several cancers, including breast cancer." (PMID 39770571, 2024). "Deficiency of TC-PTP in triple-negative primary breast cancer cells enhances cell proliferation through STAT3 signaling activation and increased Src family kinase activity." (PMID 38920657, 2024). "The EMT and metastasis of human breast cancer cells are positively linked with abnormal JAK2/STAT3 signal activation." (PMID 39079960, 2024). "Reflecting these transcriptional effects, co-activation of STAT3 and STAT5 in breast cancer is associated with the more differentiated phenotype of breast cancers than with STAT3 activation alone." (PMID 38611065, 2024). "This showed that STAT3 is the most central protein governing communication with tumor-linked proteins in the breast cancer network, whereas STAT5a is the only STAT showing a direct interaction with ER." (PMID 37834225, 2023). "LncRNAs in TDEs associated with breast cancer brain metastasis boost JAK2 activity that activates STAT3." (PMID 37514090, 2023). "STAT3 activation has been associated with a poor prognosis in breast cancer due to higher cell proliferation, migration, and survival." (PMID 37509364, 2023). "Given the association with poor outcome, inhibiting JAK/STAT3 signalling represents a promising therapeutic strategy for investigation in breast cancer." (PMID 37199043, 2023). "Aberrant activation of STAT3 has been observed in many cases of breast cancer and is associated with poor prognosis and resistance to conventional therapies." (PMID 37569363, 2023). "The silencing of STAT3 in MCF7-HER2 breast cancer cells also reduced their ability to form tumorspheres caused by the overexpression of Erb-b2 receptor tyrosine kinase 2 (ERBB2) that encodes HER2." (PMID 38067351, 2023). "As for breast cancer, high STAT3 activity is associated with a more aggressive character, while TNBC is associated with uncontrollable STAT3 activation." (PMID 37173892, 2023). "It has been reported that STAT3-mediated breast cancer cell metastasis is associated with the upregulation of vimentin, MMP-2, and MMP-9." (PMID 37836626, 2023). "In breast cancer, STAT3 activation has been associated with resistance to apoptosis, hypoxia, immune evasion and metastases in vitro." (PMID 37199043, 2023). "Overexpression and/or hyperactivity of STAT3 has been detected in 40% of breast cancer cases and is associated with a poor prognosis." (PMID 37927213, 2023). "This study has revealed a profound association between high protein expression of IL6/JAK/STAT3 signalling and worse clinical outcomes in a large retrospective cohort of breast cancer patients." (PMID 37199043, 2023). "Current understanding proposes that CAFs in HER2+ breast cancer confer resistance to Herceptin by orchestrating the loss of PTEN or activating the IL-6/STAT-3/NF-κB signaling pathway." (PMID 38001753, 2023).